CRH (corticotropin releasing hormone)
Diseases named in the same sentence as CRH in open-access papers (continued):
Sharing a sentence is not in itself a finding about the gene and the disease.
tumor (continued). "The same technique was employed to stain 3 ectopic ACTH-secreting tumours with anti-ACTH and anti-CRH antibodies." (PMID 23509456, 2013). "The underlying pathophysiological mechanism is likely related to the direct stimulatory effect of CRH on pituitary corticotrophs, which may allow for a more rapid restoration of endogenous ACTH secretion following tumor resection." (PMID 40927294, 2025). "In accordance with the selection criteria, the two groups (DDAVP and CRH) were similar in age at time of testing, tumor size, and proportions of negative MRI at diagnosis." (PMID 41422341, 2025). "68Ga-CRH PET–CT is targeting CRH receptors that not only delineate corticotropinoma and provide the surgeon with valuable information for intraoperative tumor navigation but also help in differentiating a pituitary from an extra-pituitary source of ACTH-dependent CS." (PMID 37109254, 2023). "Others propose that tumour growth is driven by the reduced negative glucocorticoid feedback on the hypothalamus with subsequent increase in corticotropin-releasing hormone (CRH) production." (PMID 36363537, 2022). "Therefore, we concluded that the tumor cell type of ACTH+&CRH + pheochromocyte from Case 1 had multiple hormone secretion functions, namely, CRH secretion function, ACTH secretion function, and catecholamine secretion function." (PMID 34905486, 2021). "Chemogenetic activation of corticotropin-releasing hormone neurons in the paraventricular nucleus of the hypothalamus (PVNCRH) neurons during specific circadian phases restores glucocorticoid rhythmicity, suppresses tumor growth, and enhances intratumoral CD8+ T cell infiltration." (PMID 41163091, 2025). "There, CRH and its receptor expression has been correlated with a higher Fédération Internationale de Gynécologie et d'Obstétrique (FIGO) stage, probably due to increased CRH-induced Fas ligand mediated local T-cell apoptosis, thus facilitating tumor immunoescape." (PMID 40917468, 2025). "Therefore, we believe that at least in nonmelanoma skin cancer, CRH does not promote tumor growth per se, but rather exerts its effects on the tumor stroma by increasing tumor vasculature and reducing an effective immune response." (PMID 40917468, 2025). "Also, it reduced the content of CORT, ACTH, CRH, and CA125, CA153, CEA in the blood, protected the pathological changes of the hippocampus and tumor, upregulated the expression of GR, CREB, and BDNF in the hippocampus, and significantly decreased the expression of NR2A, NR2B, and CaMKII." (PMID 30581482, 2018). "We believe our patient had a CRH secreting tumor due to strongly positive CRH staining, negative ACTH staining, and detectable plasma CRH." (PMID 20807418, 2010). "The percentage of tumours simultaneously expressing CRH, CRHR1 and FasL was higher in stage IV compared to stage II tumours, although this difference was not statistically significant." (PMID 17667919, 2007). "However, IHC analysis of the resected tumor revealed negative staining for ACTH and positive immunoreactivity for CRH, thereby confirming ectopic CRH secretion." (PMID 40927294, 2025). "All biochemical tests were suggestive of EAS (basal ACTH levels: 88.2 ng/L, nv 0-46; basal cortisol levels: 44.2 μg/dl, nv 4.8-19.5; negative response to CRH test and high dose dexamethasone suppression test) and radiological localization of the ectopic ACTH-secreting tumor was scheduled." (PMID 34305814, 2021). "However, immunohistochemistry of the tumor cells was negative for ACTH expression, while corticotrophin releasing hormone (CRH) was strongly expressed, suggesting that the elevated ACTH levels were a result of pituitary secretion in response to CRH." (PMID 20807418, 2010).
cancer (34 papers, 2007 to 2026). A tumor composed of atypical neoplastic, often pleomorphic cells that invade other tissues. "Interestingly, C-terminally amidated substance P and dermorphin demonstrated a significant activity, as well as CRH-linked BoT, suggesting the presence of cognate receptors in these cancer cells." (PMID 23638840, 2013). "Compiling evidence shows that CRH participates in inflammation and cancers via both indirect central effects related to stress response and direct peripheral influence." (PMID 38616821, 2024). "Instead, the central role of CRH in inflammation and cancers is mainly thought to be via mediating HPA axis as a stress mediator." (PMID 38616821, 2024). "Under these conditions, similar to the results in cancer cachexia-model mice, the percentages of NK cells were significantly decreased in the spleen of CRH-Cre::hM3Dq mice (Unpaired t-test, *** p < 0.001 vs. WT::hM3Dq group)." (PMID 38685046, 2024). "Of the 65 pathways identified for ICH and the 25 for SAH-V (current study), five overlapped including alpha adrenergic signaling, renin–angiotensin signaling, phospholipase C, corticotropin-releasing hormone signaling, and cancer mechanisms." (PMID 31595394, 2020). "Our study shows, to our knowledge for the first time, that a member of the CRH-system can undergo epigenetic silencing in a solid human cancer, hence providing new and strong evidence for a significant role of the CRH-system in human tumorigenesis." (PMID 27695045, 2016). "For this endpoint a significant interaction between gender and reason for hospitalization existed, implying that especially for CRH patients male had a higher probability to receive any type of cancer therapy." (PMID 24885104, 2014). "Human normal or cancer skin cell lines express the Crh transcript, while in the mouse skin CRH has been suggested to derive from nerve endings." (PMID 21765902, 2011). "Functional alterations of the HPA axis are a common phenomenon in patients with cancer, characterized mainly by elevated corticotropin-releasing hormone (CRH) secretion adrenocorticotropic hormone(ACTH), which leads to abnormally high levels of glucocorticoid and catecholamine." (PMID 40740866, 2025). "We therefore analyzed the effect of CRH on the proliferation and apoptosis of A431 carcinoma cells in vitro and confirmed that CRH reduces their proliferative activity and late apoptosis, two cellular characteristics typically found in differentiation processes." (PMID 40917468, 2025). "Inflammation as part of cancer progression would further up-regulate CRH expression." (PMID 37382757, 2024). "Undoubtedly, further studies are needed to verify our findings to formulate a working hypothesis of CRH-based interventions in vulvar precancer and cancer." (PMID 37382757, 2024). "Rare evidence shows a direct relationship between the central CRH and the development of cancers." (PMID 38616821, 2024). "Several lines of evidence have suggested a role of CRH in cancer." (PMID 36552294, 2022). "As with hyperactive CRF/CRH and norepinephrine tone, excessive dynorphins and kappa-opioid receptor activation in this neural network also heighten emotional-distress responses during withdrawal from opioid use and during chronic non-cancer pain." (PMID 27199787, 2016). "Furthermore, the expression of CRH has been reported in endometrial, ovarian and cervical cancer." (PMID 37382757, 2024). "Therefore, there may not be an absolute clearcut between the central and peripheral effects of CRH on inflammation and cancer." (PMID 38616821, 2024). "In addition, changes in expression both of mRNA as well protein levels have been detected for CRH-family members in a number of human malignancies such as breast, endometrial, lung, prostate and kidney cancer giving further evidence for the relevance of the CRH-system in human cancers." (PMID 27695045, 2016).
cancer (continued). "The role of these factors in other cancers is consistent with our findings, which further confirmed the potential suitability of HOXA9 and CRH status as predictors of clinical outcome." (PMID 34623790, 2021).
psychiatric disorder (34 papers, 2010 to 2026). A disorder characterized by behavioral and/or psychological abnormalities, often accompanied by physical symptoms. "Further, we discuss interactions of CRH with disrupted-in-schizophrenia 1 (DISC1), a risk factor for psychiatric disease, for which animal models indicate alteration of the CRH system." (PMID 36632608, 2022). "The dysregulation of the HPA axis has been associated with many psychiatric disorders, including hypersecretion of CRH, ACTH, and cortisol or hypoactivation of the HPA axis, marked by a blunted HPA axis response." (PMID 33318074, 2021). "Numerous psychiatric disorders are associated with the overproduction of corticotropin-releasing hormone (CRH), a peptide hormone controlling the activity of the hypothalamic-pituitary-adrenal axis (HPAA) and regulating the synthesis of adrenal steroids." (PMID 31357645, 2019). "In the remainder of this review, we will discuss studies of previously identified human polymorphisms in the CRH pathway that are associated with the occurrence of psychiatric disorders." (PMID 23077729, 2012). "Next, we present findings regarding human genetic polymorphisms in CRH pathway genes that are associated with stress and psychiatric disorders." (PMID 23077729, 2012). "Alterations in CRH expression and signaling are associated with a number of psychiatric disorders that are discussed later in this review." (PMID 23077729, 2012). "Studying the interaction of stress and polymorphisms in CRH pathway genes will enable better insight into the ability of stress to precipitate psychiatric diseases." (PMID 23077729, 2012). "Human gene variants in CRH pathways associated with psychiatric disorders." (PMID 23077729, 2012). "The CRH system has been extensively studied applying genetically engineered gain-and loss-of-function mouse models underscoring its importance for the development of psychiatric disorders." (PMID 21092110, 2010). "We propose that DISC1 influences the development and functioning of CRH neurons as a mechanism linking DISC1 to psychiatric disorders." (PMID 36632608, 2022). "The current characterization of the cell type-specific expression of CRH-BP in the PFC will serve as the basis for future studies to manipulate CRH-BP in a cell type- and subregion-specific manner to begin to define its role(s) in psychiatric disorders." (PMID 29066956, 2017). "Recent studies suggest a role for CRH-BP in stress-related psychiatric disorders and addiction, with the PFC being a potential site of interest." (PMID 29066956, 2017). "The HPA axis has long been suggested to have strong linkage to psychiatric disorders, and the role of hormones such as CRH and glucocorticoids have been considered within the understanding of the HPA axis." (PMID 23874274, 2013). "Our highlighted evidence that CRH and glucocorticoids directly affect microglia sheds new light on understanding the unsolved roles of CRH and glucocorticoids in psychiatric disorders and psychopathologies." (PMID 23874274, 2013). "The use of fMRI in investigating the functional effects of CRHR1 polymorphisms provides for greater avenues of understanding how the CRH signaling pathways affect the generation of psychiatric disorders." (PMID 23077729, 2012). "Corticotropin-releasing hormone (CRH) is a central stress hormone in the HPA axis pathway and has been implicated in stress-induced psychiatric disorders, reproductive and cardiac function, as well as energy metabolism." (PMID 23077729, 2012). "In this study, we investigated whether sex-related differences in the prevalence of psychiatric disorders could arise from variations in CRH distribution, specifically within limbic and stress-related regions." (PMID 39596070, 2024). "Moreover, several biomarkers, such as DEX/CRH, NIRS and other factors, cannot guarantee the specificity of psychiatric disorders defined by operational diagnostic criteria." (PMID 27582123, 2016).
psychiatric disorder (continued). "So far, the underlying mechanism of the mutual effects of CRH and glucocorticoids on microglia has not been well understood, while such novel knowledge will provide a systematic understanding of psychiatric disorders." (PMID 23874274, 2013). "The CRH-CRH receptor signaling pathway provides a consistent and robust series of translational studies linking basic neuroscience investigation in model systems to human psychiatric diseases." (PMID 23077729, 2012). "The data summarized in Section 4 begins to lend support to the notion that genetic variation in CRH-related pathways contributes to psychiatric disorders in humans, and could serve as a potential target for therapeutic intervention." (PMID 23077729, 2012). "CRH hyperactivity is present in several psychiatric disorders." (PMID 23077729, 2012). "Furthermore, this HPA axis dysregulation, which occurs in a subpopulation of individuals who suffer from a psychiatric disorder, is characterized by elevated secretion of ACTH and CORT that occurs in response to CRH hyperactivity." (PMID 23077729, 2012). "The possibility that non-suppression of cortisol in the DEX/CRH test might constitute a biomarker for subpopulations of a given psychiatric disorder and/or might predict a higher antidepressant treatment efficacy is under discussion." (PMID 34071053, 2021). "Stress and disturbances in the CRH system, i.e. hyperactivity and impaired negative feedback regulation of the HPA axis, are frequently accompanying psychiatric disorders including depression and anxiety." (PMID 21092110, 2010).
infection (23 papers, 2009 to 2026). The state of being infected such as from the introduction of a foreign agent such as serum, vaccine, antigenic substance or organism. "The results showed that high infection rates in AVP-positive neurons (56.68%) and CRH-positive neurons (25.93%), whereas infection of OXT-positive neurons was minimal (9.09%)." (PMID 41543628, 2026). "The median duration of LC symptoms was 1118 days (IQR, 964.5–1331), with a similar interval from index infection in the CRH cohort." (PMID 41255761, 2025). "The secretion of corticosteroids is regulated by the hypothalamic–pituitary–adrenal (HPA) axis, and stressors such as cold, infection, and hemorrhage stimulate the hypothalamus to release more corticotropin-releasing hormone (CRH)." (PMID 40217593, 2025). "In contrast, mice administered CRH 18 h after infection resulted in a significantly higher survivorship compared to all experimental groups." (PMID 28057851, 2017). "Accordingly, administration of antalarmin led to a significantly higher increase in the total leukocyte count compared to CRH and infection alone." (PMID 28057851, 2017). "Exposing S. pneumoniae cultures to CRH prior to experimental infection produced greater pulmonary bacterial burden compared to infection with untreated cultures." (PMID 25904910, 2015). "Furthermore, intrauterine infection through ascending infection during pregnancy stimulates the secretion of proinflammatory cytokines and chemokines, prostaglandins, and MMPs in the mother and corticotropin-releasing hormone in the fetus." (PMID 38542370, 2024). "We next tested the hypothesis that survival is predicted by the type of cellular inflammatory response produced during infection given intranasal administration of CRH." (PMID 28057851, 2017). "Moreover, infection of mice with CRH-treated S. pneumoniae resulted in greater bacterial carriage in the lung." (PMID 25904910, 2015). "Physiological stress, such as that caused from infections, may also be part of activation of placental CRH pathways, but the role of CRH in response to infection remains elusive." (PMID 26334745, 2015). "Moreover, a fetal response takes place as the infection promotes the release of the corticotropin-releasing hormone and, subsequently, the release of fetal corticotropin and fetal cortisol from both the placenta and the fetal hypothalamus, resulting in prostaglandin production." (PMID 38674294, 2024). "So, CRH can been found in several peripheral tissues and may be involved in the regulation of the distribution of immune cells after acute stress or infection." (PMID 36338491, 2022). "After MIA induction by infection, IL-6 in maternal serum is elevated, and placental SOCS3 and CRH are upregulated in response to the increased IL-6." (PMID 34350170, 2021). "Corticotropin Releasing Hormone (CRH) is a 41-amino acid neuropeptide secreted from the HPA, and stimulates the release of adrenal cortisol in response to infection and other stressors." (PMID 28690980, 2017). "Here we demonstrate that inhibition of MyD88 and TRIF signaling block cAMP-induced CRH promoter activation in the JEG3 cells in the absence of infection." (PMID 19615077, 2009). "Here, our aim is to further examine the role of MyD88 and TRIF in cAMP-induced CRH promoter activation in the absence of infection or TLR stimulation." (PMID 19615077, 2009). "MyD88 and TRIF exert direct regulatory effect on cAMP-induced CRH promoter activation in JEG3 cells in the absence of infection." (PMID 19615077, 2009). "We further investigated conserved signaling pathways, CRH-1/CREB, AAK-2/AMPK, and JNK-1/JNK, results revealed that Berberine hydrochloride enhanced survival in crh-1(tz2), aak-2(ok524), and jnk-1(gk7) mutants after infection, similar to its effects in wild-type worms." (PMID 40092994, 2025).
inflammation (7 papers, 2013 to 2025). Aberrant reaction of the microcirculation characterized by movement of fluid and leukocytes from the blood into extravascular tissues. "Another reason is probably because the anti-inflammatory effect of CRH depends on CRHR2 which induces a proinflammatory effect during acute colitis but confers protective activity during chronic inflammation." (PMID 30881446, 2019). "A previous study on intestinal inflammation showed that CRH via CRHR1 increased phosphorylation of Akt in human intestinal microvascular endothelial cells." (PMID 26110874, 2015). "For instance, orthologs for CRH and urocortins, Substance P, NPY, alpha-MSH, ghrelin and GIP have been described in zebrafish and in parallel implicated in the pathogenesis of intestinal inflammation, in mouse and human studies." (PMID 24376661, 2013). "In this case, gut inflammation may not directly influence the brain, but the release of pro-inflammatory cytokines and stress-related hormones like corticotropin-releasing hormone (CRH) can elicit CNS responses, which may affect mood and behavior." (PMID 41010510, 2025).
brain disorder (3 papers, 2022 to 2024). A disease affecting the brain or part of the brain. "Subgenual anterior cingulate cortex (sgACC) of human subjects without brain disorders were labeled using fluorescent in situ hybridization (FISH) for CRH and markers of excitatory (SLC17A7), inhibitory (GAD1) neurons, as well as markers of other interneuron subpopulations (PVALB, SST, VIP)." (PMID 35280164, 2022). "However, Spierling and Zorrilla emphasized that we still do not fully understand CRH role, especially related to brain disorders." (PMID 35275963, 2022).
cardiovascular disease (3 papers, 2015 to 2024). "Our mathematical modeling could also be extended to interrogate other physiological phenomena such as the mechanisms by which the PVN CRH neural system underlies the adverse outcomes of nutritional programming on cardiovascular disease." (PMID 38264285, 2023). "A well-known function of CRH is HPA axis regulation, and hyperactivity of the HPA axis is a characteristic of chronic diseases, including cardiovascular disease." (PMID 26110874, 2015).
neurological disorders (3 papers, 2019 to 2024). "Therefore, our results should be valuable to guide further investigations of the functional roles of the ACC CRH neurons, such as the normal and neurological disease states." (PMID 31213976, 2019).
bacterial infection (2 papers, 2014 to 2017). "Determining the mechanism of action of CRH on particular inflammatory cells will provide a novel understanding of mechanisms mediating cellular immune inflammatory responses caused by severe bacterial infections." (PMID 28057851, 2017).